TRIM28 (tripartite motif containing 28)
Description:
E3 SUMO and ubiquitin ligase that plays a pivotal role in embryonic development, genomic imprinting, and maintenance of genomic stability through repression of repetitive and retroviral elements. Also involved in DNA repair, regulation of innate immunity or cellular energy homeostasis. Acts as a scaffold for assembling transcriptional repression complexes containing methyltransferases, histone deacetylases, and chromatin remodelers. Serves as a nuclear corepressor for KRAB domain-containing zinc finger proteins (KRAB-ZFPs), mediating gene silencing by recruiting CHD3, a subunit of the nucleosome remodeling and deacetylation (NuRD) complex, and SETDB1, which methylates histone H3 at Lys-9 (H3K9me), leading to heterochromatin formation. In collaboration with SETDB1, is also required for H3K9me3 and silencing of endogenous and introduced retroviruses in a DNA-methylation independent-pathway (By similarity). Functions as a coactivator for CEBPB and NR3C1 (glucocorticoid receptor) in transcriptional activation of ORM1, and as a corepressor for ERBB4. Inhibits E2F1 activity by promoting E2F1-HDAC1 complex formation and preventing E2F1 acetylation. This contributes to CDKN1A/p21(CIP1) regulation and provides a partial backup to suppress E2F1-mediated apoptosis in the absence of RB1. Mediates the nuclear localization of several KRAB-ZFP transcription factors including KOX1, ZNF268, and ZNF300 among others. In association with isoform 2 of ZFP90, is required for the transcriptional repressor activity of FOXP3 and the suppressive function of regulatory T-cells (Treg). Required to maintain a transcriptionally repressive state of genes in undifferentiated embryonic stem cells (ESCs). Acts as a corepressor for ZFP568. Beyond its nuclear functions, acts as a positive regulator of type I interferon (IFN-I) signaling by promoting Lys-63-linked ubiquitination of TBK1, facilitating TBK1-IRF3 complex formation. Mediates TRAF6 SUMOylation to regulate its nucleo-cytoplasmic shuttling and modulate activation of the canonical NF-kappa-B signaling pathway. Facilitates SUMOylation of NLRP3, protecting it from 'Lys-48'-linked ubiquitination and proteasomal degradation and thereby enhancing inflammasome activation. (Microbial infection) Plays a critical role in the shutdown of lytic gene expression during the early stage of herpes virus 8 primary infection. This inhibition is mediated through interaction with herpes virus 8 protein LANA1. (Microbial infection) Plays a positive role in SARS-CoV-2 virulence by mediating SUMOylation of nucleoprotein that promotes its RNA association leading to viral replication and innate antiviral immunity inhibition.
Synonyms: TIF1-beta; KAP-1; KAP1; RNF96; TIF1B; TF1B; PPP1R157; TIF1beta; WT7
Tractability: Small molecule: it has a binding pocket of medium quality. PROTAC: UniProt records ubiquitination sites on it; ubiquitination databases record sites on it; its protein half-life has been measured.
Target class: Epigenetic regulator; Bromodomain; Reader
Gene: Protein-coding gene on chromosome 19 (58,543,740 to 58,550,773, forward strand). Ensembl gene ENSG00000130726.
Subcellular location: Nucleus
Subcellular location (Human Protein Atlas): Nucleoplasm
Pathways (Reactome):
Gene expression (Transcription): Generic Transcription Pathway; Regulation of endogenous retroelements by KRAB-ZFP proteins
Disease: HCMV Early Events
Metabolism of proteins: SUMOylation of transcription cofactors
Gene Ontology:
Molecular function: chromatin binding; chromatin-protein adaptor activity; chromo shadow domain binding; DNA binding; Krueppel-associated box domain binding; promoter-specific chromatin binding; protein binding; RNA binding; SUMO ligase activity; SUMO transferase activity; transcription corepressor activity; ubiquitin protein ligase activity; ubiquitin protein ligase binding; ubiquitin-protein transferase activity; zinc ion binding; transcription coactivator activity; protein kinase activity; transcription coregulator activity
Biological process: antiviral innate immune response; DNA damage response; DNA methylation-dependent constitutive heterochromatin formation; DNA repair; negative regulation of canonical NF-kappaB signal transduction; negative regulation of DNA-templated transcription; positive regulation of DNA repair; positive regulation of protein import into nucleus; positive regulation of type I interferon production; proteasome-mediated ubiquitin-dependent protein catabolic process; protein sumoylation; protein ubiquitination; suppression of viral release by host; chromatin organization; epithelial to mesenchymal transition; innate immune response; positive regulation of DNA-templated transcription
Cellular component: chromatin; nucleoplasm; nucleus; protein-containing complex; RNA polymerase II transcription regulator complex; euchromatin; heterochromatin
Genetic constraint (gnomAD): Loss-of-function variants: 8 observed, 85.15 expected, observed/expected ratio (o/e) 0.094, 90% interval 0.054 to 0.17. The synonymous counts are far from expectation, so gnomAD's model fits this gene poorly and the ratio says little. Missense variants: 968 observed, 1,109.9 expected, observed/expected ratio (o/e) 0.87, 90% interval 0.83 to 0.92. Synonymous variants: 601 observed, 443.48 expected, observed/expected ratio (o/e) 1.36, 90% interval 1.27 to 1.45.
Homologues: Orthologues: chimpanzee TRIM28 (100% identical), macaque TRIM28 (99% identical), dog TRIM28 (97% identical), pig TRIM28 (96% identical), mouse Trim28 (94% identical), rat Trim28 (94% identical), guinea pig Trim28 (92% identical), rabbit TRIM28 (88% identical), tropical clawed frog trim28 (51% identical), zebrafish trim33l (21% identical). Paralogues in human: TRIM33 (32% identical), TRIM24 (29% identical), TRIM66 (22% identical), TRIM71 (14% identical), TRIM2 (13% identical), TRIM56 (12% identical), TRIM3 (12% identical), TRIM46 (12% identical), TRIM37 (11% identical), MID1 (11% identical), PML (11% identical), TRIM9 (11% identical), and 68 more.
Diseases named in the same sentence as TRIM28 in open-access papers:
TRIM28 is named in the same sentence as 135 diseases in open-access papers, as found by Europe PMC text mining. Sharing a sentence is not in itself a finding about the gene and the disease. The quoted sentences say what the papers report.
breast cancer (39 papers, 2015 to 2026). A primary or metastatic malignant neoplasm involving the breast. "We have recently reported that TRIM28 overexpression closely associates with cancer stemness in breast cancer and melanomas and subsequently demonstrated that this phenomenon is very universal across diverse types of solid tumors." (PMID 35049055, 2022). "TRIM28 was recently associated with breast cancer stem cells through the link to a novel long noncoding RNA named BORG." (PMID 35205738, 2022). "The co-repressor function of TRIM28 have been shown recently to be linked to the development of various cancers, such as non-small cell lung cancer, breast cancer, cervical cancer, colon cancer, gastric cancer, and ovarian cancer." (PMID 34419074, 2021). "Hao L found that TRIM28 is frequently elevated in multiple tumor types and is associated with aggressive clinical features of breast cancer." (PMID 30484263, 2019). "High level of TRIM28 is associated with triple-negative subtype of breast cancer (TNBC), which shows higher aggressiveness and lower survival rates." (PMID 27845900, 2017). "We conclude that impaired mitochondrial functions and “metabolic switch” from OXPHOS to glycolysis results in loss of self-renewal of breast cancer stem cell and lead to tumor growth inhibition of upon TRIM28 knockdown." (PMID 27845900, 2017). "Along these lines, BORG:TRIM28 complexes are necessary for reprogramming the transcriptional signatures of latent breast cancer cells to align with those associated with a more aggressive and metastatic phenotype." (PMID 28983112, 2017). "The downregulation of TRIM28 expression results in a loss of the stem cell-like phenotype in melanoma and breast cancer, although the TRIM28-mediated stemness-high tumor phenotype might be a universal phenomenon across distinct cancer types." (PMID 33810347, 2021). "Finally, in order to explore the diagnostic usefulness of TRIM28 in BC, IHC scores in 114 cases of breast cancer tissues and the corresponding adjacent normal tissues were included in the study." (PMID 33817325, 2021). "For example, in breast cancer, three cohorts indicated that higher TRIM28 levels were marginally associated with poorer DFS and DSS, but two other datasets demonstrated that lower TRIM28 levels were associated with poorer DMFS and OS in the PrognoScan database." (PMID 33091876, 2020). "We have shown that downregulation of TRIM28 expression results profound changes in breast cancer xenografts including: loss of pluripotency and mesenchymal markers, inhibition of stem cell-associated signaling pathways, reduced ability to induce tumor growth and reduced number of cancer stem cells." (PMID 27845900, 2017). "Coupled with the genome-wide analyses presented herein, such studies also define the function of TRIM28 as an RNA-binding protein, while simultaneously providing a global picture of candidate loci associated with the suppression or promotion of breast cancer metastasis." (PMID 28983112, 2017). "The binding of BORG to TRIM28 was previously shown to promote the repressive transcriptional activity of TRIM28, which binds to the p21 and gadd45a loci, inducing substantial alterations in the proliferation and survival of breast cancer cells." (PMID 41181715, 2025). "In the present study, we found that dynamic SUMOylation of MORC2 by TRIM28 orchestrates chromatin remodeling and DNA repair in response to DNA damage and drives chemoresistance in breast cancer." (PMID 36793866, 2023). "We have previously demonstrated that the metabolic changes abolished the self-renewal potency of breast cancer stem cells and led to the inhibition of tumor growth upon TRIM28 knockdown." (PMID 36674511, 2023).
breast cancer (continued). "For example, TRIM28 was reported to promote cell proliferation in breast cancer and inhibit cell proliferation in early-stage lung cancer." (PMID 36935008, 2023). "RNA sequencing of knockdown subclones revealed that hypoxic induction of the vast majority of HIF-regulated genes in human breast cancer cells is dependent on TRIM28 and DNA-PK." (PMID 35031618, 2022). "BORG promotes breast cancer stem cell phenotypes through its ability to physically interact with TRIM28." (PMID 35205738, 2022). "TRIM28 knockdown in MDA-MB-231 breast cancer cells decreases the number of CSCs and their tumorigenicity in the xenograft assay." (PMID 36077272, 2022). "Schiemann reported that lncRNA BORG regulates the transcriptional repressive activity of TRIM28 to trigger the migration and invasion of potential breast cancer cells." (PMID 34134612, 2021). "Our data demonstrate that the previously reported involvement of TRIM28 in the regulation of a stem-cell like phenotype in melanoma and breast cancer is a common phenomenon across distinct types of solid tumors." (PMID 33810347, 2021). "TRIM28 expression is elevated in a variety of tumours, including breast cancer, gastric cancer and lung cancer." (PMID 34500575, 2021). "Of all 114 samples, 18 (15.8%) were triple-negative breast cancer, whose immunohistochemical score was significantly higher than that of non-triple-negative breast cancer (P = 0.01), suggesting that the expression level of TRIM28 was associated with molecular subtypes in BC." (PMID 33817325, 2021). "From the ROC curve analysis, it can be proved that the expression level of TRIM28 can distinguish breast cancer tissues from normal ones." (PMID 33817325, 2021). "We have previously shown that high TRIM28 expression is strictly related to the stem cell-like phenotype of breast cancer and melanomas." (PMID 33810347, 2021). "The upregulation of TRIM28 predicts a poor prognosis in patients with gastric cancer, ovarian cancer, breast cancer and colorectal cancer." (PMID 33091876, 2020). "Tripartite motif-containing protein 28 (TRIM28; also known as KRAB-associated protein 1 or KAP1) was previously shown to promote breast cancer proliferation and metastatic progression and required for maintenance of mouse ESC pluripotency and self-renewal." (PMID 33327550, 2020). "TRIM28 protein expression was upregulated in breast cancer, colon cancer, ovarian cancer, clear cell renal cell carcinoma, uterine corpus endometrial carcinoma and LUAD." (PMID 33091876, 2020). "Our original results revealed the role of the TRIM28 in regulating the CSC population in breast cancer." (PMID 27845900, 2017). "Recently, the indispensable role of TRIM28 for maintaining breast cancer stem cell population has been reported." (PMID 28851455, 2017). "Here, we demonstrated that TRIM28-depletion in breast cancer cells lead to significant reduction of tumor growth in vivo." (PMID 27845900, 2017). "Mechanistically, BORG elicits the metastatic outgrowth of latent breast cancer cells by promoting the localization and transcriptional repressive activity of TRIM28, which binds BORG and induces substantial alterations in carcinoma proliferation and survival." (PMID 28983112, 2017). "Altogether, these results confirmed the involvement of TRIM28 protein in the maintenance of the CSC population in breast cancer." (PMID 27845900, 2017). "Following on that finding, we evaluated the role of TRIM28 protein in the regulation of breast cancer stem cells (CSC) populations and tumorigenesis in vitro and in vivo." (PMID 27845900, 2017). "TRIM28 depletion in MCF7 breast cancer cell line in vitro resulted in significant inhibition of CD44+CD24−/low mammosphere formation, which correlated with decreased expression of stem-cell associated genes." (PMID 28851455, 2017). "The major finding of our study is novel role of TRIM28 protein in tumorigenesis of breast cancer through regulation of the self-renewal of CSC." (PMID 27845900, 2017).
breast cancer (continued). "Here we report that a TRIM28-TWIST1-EMT axis exists in breast cancer cells and TRIM28 promotes breast cancer metastasis by stabilizing TWIST1 and subsequently enhancing EMT." (PMID 27412325, 2016). "Given the fact that TWIST1 is an important regulator of cell migration and invasion and its expression is highly correlated with the levels of TRIM28 in breast cancers, we decided to explore the effects of TRIM28 on cell migration and invasion." (PMID 27412325, 2016). "We unexpectedly noticed that in 4T1 mouse breast cancer cells ectopically expressed TRIM28 is capable of enhancing the protein level of Twist1 and meanwhile repressing its mRNA level." (PMID 27412325, 2016). "Identification of the TRIM28-TWIST1-EMT axis in breast cancer cells makes TWIST1 a potential therapeutic target for breast cancer treatment." (PMID 27412325, 2016). "Based on the role of TRIM28 in EMT, we propose that in breast cancer cells exist a TRIM28-TWIST1-EMT axis which plays an important role in breast cancer metastasis." (PMID 27412325, 2016). "Then we overexpressed TRIM28 in 4T1 mouse breast cancer cells which express low levels of endogenous TRIM28 by transiently transfection of plasmid either expressing Flag-tagged TRIM28 or the empty vector as a control." (PMID 27412325, 2016). "We propose that in breast cancer cells exist a TRIM28-TWIST1-EMT axis which plays important roles in breast cancer metastasis." (PMID 27412325, 2016). "In this study, we first showed that comparing to that in the normal adjacent tissues TRIM28 mRNA is significantly higher in breast cancer tissues." (PMID 27412325, 2016). "We find that TRIM28 is highly expressed in both cancer cell lines and advanced breast cancer tissues, and the levels of TRIM28 and TWIST1 are positively correlated with the aggressiveness of breast carcinomas." (PMID 27412325, 2016). "Recently, it has been reported that TRIM28 is capable of promoting breast cancer cell proliferation and metastatic progression." (PMID 27412325, 2016). "Upregulation of TRIM28 (also known as TIF1β) and TRIM25 is associated with a poor prognosis in gastric cancer and breast cancer, respectively." (PMID 26247633, 2015). "Moreover, BORG:TRIM28 complexes also govern the self-renewal and expansion of breast cancer stem cells, doing so by inducing the expression of Nanog, Aldh1a3, and Itga6/α6 integrins." (PMID 39335212, 2024). "TRIM28 has been reported to play an important role in breast cancer stem cells (BCSCs)." (PMID 36756159, 2023). "Moreover, in breast cancer cells, TRIM28 can enhance EMT by stabilizing TWIST1 to promote breast cancer metastasis." (PMID 36756159, 2023). "Other mechanisms could involve TRIM28, the phosphorylation of which was shown to downregulate Mfn2 in response to starvation-induced oxidative stress in breast cancer cells." (PMID 33757833, 2021). "However, TRIM28 expression had less of an impact on the prognosis of ovarian cancer and breast cancer." (PMID 33091876, 2020). "Research into the correlation between TRIM28 expression and prognosis in patients with cancer, Hao L demonstrated that high expression of TRIM28 is a predictor of poor prognosis in patients with breast cancer." (PMID 30484263, 2019). "Furthermore, the overexpression of TRIM28 was significantly correlated with poor prognosis in patients with breast cancer." (PMID 30484263, 2019). "MAGEC2 has recently been reported to bind to TRIM28 in breast cancer cell lines HTB126 and HCC1806." (PMID 30309319, 2018). "Interestingly, the ability of TRIM28 to enhance the malignancy of breast cancer cells transpires in part through its transcriptional repression of both p21 and gadd45a15,16,18, two transcripts whose expression is negatively regulated by BORG in D2.OR cells." (PMID 28983112, 2017). "Moreover, TRIM28 protein is involved in the transcriptional activation of EMT program, which is linked to the acquisition of stem cell properties in breast cancer." (PMID 27845900, 2017).